AR (androgen receptor)
Diseases named in the same sentence as AR in open-access papers (continued):
Sharing a sentence is not in itself a finding about the gene and the disease.
tumor (continued). "Altogether, these results suggest that in androgen-dependent LNCaP cells, inhibition of AR may allow the tumor cells to activate the Wnt/β-catenin pathway." (PMID 26509262, 2015). "Finally, our model suggests that in tumour cells harbouring an ERG gene fusion iii) AR activation of the ERG fusion gene creates a dynamic negative feedback loop impacting on both the AR and HES6, creating a more complex transcriptional network." (PMID 25560400, 2015). "Preclinical data showed that targeting mTOR along with antiandrogen treatment exhibited additive antitumor effects in a prostate-specific Pten (pseudogene of the tumor suppressor)-deleted mouse model, supporting the rationale for combining AR and mTOR inhibitors to treat CRPC." (PMID 26690121, 2015). "Targeting the tumor microenvironment and the stromal AR could be attractive as a therapeutic strategy because of its critical involvement in PCa." (PMID 25793207, 2015). "Additionally, the concordance rate of AR expression between the different tumor sites was determined." (PMID 26552477, 2015). "Collectively, these data highlight the complexity during transcriptional activation of AR due to alteration in the microenvironment of prostate cells that could trigger normal as well as tumor growth." (PMID 26295410, 2015). "Tumor growth due to AR activity was also shown for apocrine BCs." (PMID 26552477, 2015). "Post-translational modification of the AR represents an additional level of receptor regulation with acetylation of key residues in the hinge region of the receptor playing a pivotal role in contact-independent growth and tumour development in vivo." (PMID 26267320, 2015). "HOXB13, which encodes the transcription factor 13, belongs to the HOXB gene cluster at chromosome 17, involves in embryonic development of different organs, regulates transcription of androgen receptor (AR) target genes and is reported to function as a tumor suppressor in cancer." (PMID 26517352, 2015). "The findings also substantiate the dominant role of Sp1 in driving AR expression and thus reinforce the rationale of targeting this transcription factor, as this action will promote binding of competing pur-α and inhibit tumour progression." (PMID 26448047, 2015). "In addition, activation of AR through crosstalk with kinase signaling pathways has been postulated as a potential mechanism for recurrent tumor growth in the castrate environment." (PMID 25950519, 2015). "The HBC-mediated suppression of tumor growth is due to the suppression of proliferation since the expression of AR and cyclin A required for proliferation were suppressed and the expression of p27, which negatively regulates proliferation, was induced in tumor tissues." (PMID 25704883, 2015). "Older studies suggest that a small minority of NE tumor cells display some AR expression." (PMID 25785244, 2015). "Importantly, inhibiting BRD4 or MLL results in an anti-tumor effect in AR signaling-competent models of CRPC." (PMID 26566796, 2015). "The rise in the PSA level, which may signal AR reactivation in tumor cells, occurs after a median of 8–10 months of treatment." (PMID 25950519, 2015). "Multiple mechanisms of AR activation in CRPC tumor cells have been characterized." (PMID 25950519, 2015). "Collectively these data suggest that the tumour promotional activation of AR may be an adaptive response primarily in cancers exhibiting dysregulated estrogen signalling." (PMID 26341737, 2015). "Clioquinol, a therapeutic agent for Alzheimer's disease, is able to target tumor proteasome in vivo in a copper-dependent manner, resulting in formation of an active AR inhibitor and apoptosis inducer that is responsible for its observed antiprostate tumor effect." (PMID 26097878, 2015). "In ER-positive tumours it is reported that androgen receptor (AR) expression is beneficial and it is suggested that it may compete for ER binding sites on the DNA, thereby blocking estrogen-stimulated transcription of pro-proliferative genes." (PMID 26341737, 2015).
tumor (continued). "Furthermore, clear anti-tumour activity of ISIS-ARRx in these models provides preclinical support for AR-ASO strategies as a rational third-line approach for AR pathway inhibitor-resistant CRPC." (PMID 25896606, 2015). "Our finding that infiltrating pre-adipocytes could induce miR-301a to promote PCa metastasis via down-regulating AR, represents another new mechanism for miR-301a to alter the tumor progression." (PMID 25940439, 2015). "In addition, and as expected, there was a modest up-regulation of ERβ (a PC tumor suppressor), as a consequence of AR depletion." (PMID 26196320, 2015). "Castration resulted in significantly reduced tumor cell proliferation in both PShTert-AR (p<0.01) and PShTert-ctrl myofibroblast (p<0.001) grafts, a reduction in cancer p63−/CK8.18+ foci, and a higher percentage of apoptotic cancer cells (caspase-3 positive; p<0.001)." (PMID 25965833, 2015). "Through reactivation of the AR signaling pathway during hormone therapy, the balance between the proliferation and apoptotic cell death of PC cells is disturbed, which further drives tumor progression toward castration resistance." (PMID 26690121, 2015). "Hyperactivation of androgen receptor pathway (AR) plays a central role in the tumor development." (PMID 26491211, 2015). "Treatment of the tumors with the taxane docetaxel showed that the drug inhibited tumor growth of the LuCaP 86.2 cells but not of the LuCaP 23.1 cells, indicating that expression of splice variants of the AR can affect sensitivity to docetaxel." (PMID 26401448, 2015). "Since a downstream effector of re-activated AR signalling in CRPC tumors is acceleration of tumor cell mitosis, targeting both cancer cell cycling and AR transcriptional activity may more strongly inhibit CRPC growth." (PMID 26009876, 2015). "Furthermore, TLN1 K/D significantly delayed growth of highly aggressive AR tumor (median survival, NT shRNA-AR, 21 days and shTLN1-AR, 28 days, p < 0.001)." (PMID 26336988, 2015). "Unfortunately, for PCa researchers many of the current mouse models fail to fully recapitulate human disease progression; i.e., an AR-dependent tumor growing in the prostate gland that spontaneously metastasizes to the bone to from an AR-dependent osteoblastic cancer." (PMID 25566502, 2014). "Although such contrasting findings may depend on several factors, one possible explanation may be related to a different role of AR depending on its location (stroma or epithelium) in the tumor." (PMID 24744780, 2014). "However, significant differences were generally not observed in recurrent tumors resected at late time points, consistent with the increase in AR expression and reconstitution of tumor androgen levels observed in these samples." (PMID 25356728, 2014). "In addition, the androgen receptor was expressed in the tumor cells, thus the lesion was diagnosed as an SCC of the breast, exhibiting apocrine features." (PMID 24520287, 2014). "The presence of androgen synthesizing pathway in addition to AR expression in tumor cells (AR+/enzyme+) could confer a better clinical outcome through suppression of cell proliferation." (PMID 24978437, 2014). "Interestingly, AUY922 as a single treatment and in combination with docetaxel showed that Hsp90 inhibition had a heterogeneous effect overall on tumor AR expression." (PMID 25072314, 2014). "Finally, the growth and AR expression of seven groups of tumor tissues were assessed using the C4-2 xenograft mouse model." (PMID 24798477, 2014). "Since AR is diminished in metastatic LNCaPRANKL cells compared to their parental LNCaPNeo cells, we tested the possibility of restoring AR activity by growing LNCaPRANKL cells in in vivo as tumor xenografts or 3-D suspension cultures." (PMID 25200184, 2014). "Loss of AR expression in the tumor stroma, but not in the surrounding normal prostatic stroma tissue, increases the risk of relapse following radical prostatectomy." (PMID 25646090, 2014).
tumor (continued). "Interestingly, AR re-expression has been also achieved following chronic exposure (20 days) to 5-Aza-CR, resulting in a marked decrease of tumor cell proliferation and a significant increase of AR and PSA protein levels." (PMID 24797896, 2014). "Nonetheless, in preclinical studies with AZD3514, and utilising the same scoring structure as the present method (0+, 1+, 2+ and 3+), IHC was able to demonstrate a dose dependent reduction on AR in tumour tissue, at doses of drug that produced only a modest inhibition of tumour growth." (PMID 24674711, 2014). "Ectopic expression of FKBP5 (flag-FKBP5) induced AR expression in non-tumor HEK293T cells." (PMID 25460502, 2014). "In PCa, STAT3 activation associated with decreased AR expression is mediated through increased production of IL-6 and treating mice with soluble IL-6 receptor fusion protein significantly reduces CSC number and xenograft tumor growth." (PMID 24722453, 2014). "Therefore, the potential detrimental effects of androgen deprivation therapy (ADT) on PCa tumour development through increased AR transcription should be borne in mind." (PMID 24895212, 2014). "Additionally AR-activity was inhibited by both stilbenes as depicted by a down regulation of PSA in the tumor xenografts (PSA expressing LNCaP cells, untreated 100%, 100 μM RSV 27+/−24%, 50 μM FIDAS 64+/−29%)." (PMID 24887556, 2014). "Therefore, bicalutamide reduced PSA expression in the bone-niche and up-regulated AR expression while tumor growth was largely unaffected." (PMID 25278011, 2014). "In this study, a bioinformatics approach was developed, and it demonstrated that the function-unknown protein ovarian carcinoma immunoreactive antigen-like protein 2 (OCIAD2) is probably regulated by TGFβ and AR signals in the tumor EMT process." (PMID 24949437, 2014). "However, in our material, cases with levels of both tumour ErbB2-IR and AR-IR above the median were less common in patients with stage 3 tumours (n = 58) than for stage 2 tumours (n = 82)." (PMID 25215939, 2014). "Our molecular findings suggest that the CRPC cells may bypass the suppressive effects of Nrf2 on AR transactivation during ADT by selecting for tumor clones with decreased Nrf2 expression." (PMID 24466341, 2014). "Expression of TMPRSS2-ERG fusion shows a striking correlation with AR expression in tumor biopsies." (PMID 25277175, 2014). "With pbMOO approach, the functional unknown protein OCIAD2 was also enrolled into a signal pathway “TGFβ1- TGFβR1- SMAD2/3- SMAD4- AR-OCIAD2” in tumor and adjacent microenvironment." (PMID 24949437, 2014). "Tumoral LC3A positivity was significantly associated with higher histologic grade (P<0.001), higher Ki-67 LI (P<0.001), AR negativity (P<0.001), and HER-2 negativity (P<0.001), while stromal LC3A positivity showed a significant relationship with HER-2 positivity (P<0.001)." (PMID 25140630, 2014). "Our data in clinical specimens suggest that the ratio of nuclear AR to ER may critically influence tumor biology and response to endocrine therapy." (PMID 24451109, 2014). "Previous studies also showed that AR expression was tumor stage-dependent." (PMID 25535400, 2014). "We showed here that TGF-β could indirectly induce AR activation in PCa cells through directly modulating stromal cells in tumor microenvironment." (PMID 25333263, 2014). "Roughly ten different major signal transduction pathways can drive tumor growth: estrogen and androgen receptor pathways (ER, AR), the developmental pathways Wnt, Notch, Hedgehog, TGFbeta, and FGF, the inflammatory NFkappaB pathway, and a number of related growth factor PI3K pathways." (PMID 24879438, 2014). "Tumour stages for patients with different tumour epithelial ERBb2-AR and AR-IR scores." (PMID 25215939, 2014). "Notably there are also changes in the tumor stroma related to tumor aggressiveness (for example decreased androgen receptor expression and mast cell numbers) that are apparently unrelated to epithelial ERG status." (PMID 24505269, 2014).
tumor (continued). "Given the 5–10 fold higher potency of DHT for engaging and activating AR relative to T, we estimated an ‘absolute androgenicity index’ to more accurately model the total steroid ligand contribution present in each tumor, calculated as the sum of (5xDHT) + (1xT)." (PMID 25356728, 2014). "In this study, we show that the use of an Hsp90 inhibitor achieves inhibition of AR expression and transcriptional activity, which allows for sensitization to docetaxel chemotherapy and greater anti-tumor activity through the induction of tumor cell death." (PMID 25072314, 2014). "Adhesion of PCa tumor cells to laminin to engage α6β1 promoted AR-dependent survival of the cells." (PMID 25566502, 2014). "Thus, 9% of cases with tumour stage 3 had low expression levels of both AR-IR and ErbB2-IR, whilst 73% of the cases had high expression levels of both parameters." (PMID 25215939, 2014). "AR immunoreactivity was observed in the nuclei of tumor cells." (PMID 24403250, 2013). "The percentage of tumor cells with AR expression differed by age in ER-positive cases." (PMID 24403250, 2013). "Thus, the contribution of AR-driven Ets activation and the mechanisms that drive tumor initiation and tumor progression are in need of much further investigation." (PMID 24199173, 2013). "To investigate the role of AR and mimic the crosstalk between macrophages and PCa cells in the tumour microenvironment, we established an in vitro co-culture model that allows the crosstalk between infiltrating macrophages and PCa cells in the presence or absence of AR silencing." (PMID 23982944, 2013). "In this study, we investigated genistein action on two other tumor-derived AR proteins; W741C-AR and H874Y-AR that were identified in patients with metastatic androgen-independent disease following androgen ablation therapy and have been shown to respond to various non-androgenic steroids." (PMID 24167630, 2013). "Notch as a tumor suppressor may be mediated through Hey2/L expression, which then acts as an AR co-repressor." (PMID 24199173, 2013). "In addition, intra-tumor variation was evident by both the AR and PTEN markers, which showed greater heterogeneity from tumors at the prostate site than distant metastases." (PMID 24098661, 2013). "Interestingly, although targeting PCa AR alone in TRAMP-C1 cells significantly reduced the tumour volume, we found mice with AR silenced TRAMP-C1 tumours had increased liver and diaphragm metastases." (PMID 23982944, 2013). "After all, the main trait of MA tumors is the activation of the AR pathway, and AR target genes could help to identify this tumor subgroup." (PMID 23663520, 2013). "When AR gene amplification and mutations were shown by in situ studies, enzalutamide and ARN-509 were developed to abrogate the actions of AR in facilitating tumor progression." (PMID 23819055, 2013). "Our results indicated that the positive PA1-nuc staining was significantly associated with postmenopausal group (P = 0.0097), smaller tumor size (P = 0.0025), negative Ki67 (P = 0.02), positive AR (P = 0.049), and positive ERβ (P = 0.0020) status." (PMID 24260416, 2013). "To explore whether genistein activity extends to other tumor-derived mutant ARs, we examined genistein effects on the proliferation of PC-3 cells we transiently transfected with two other AR mutants with promiscuous binding features (W741C and H874Y)." (PMID 24167630, 2013). "In addition, monitoring of tumor PR, ER, and AR expression at the time of recruitment will be important." (PMID 23484104, 2013). "It is possible that via modulation of EMT, this could explain the slower growth of AR silenced PCa cells since invasive tumour cells with EMT often manifested slow proliferation with lower expression of Ki67 and increased cell cycle inhibitor, p16/INK4A." (PMID 23982944, 2013). "Persistent AR signaling along with dowregulation of eIF2α-P may lead to AR-mediated transcriptional events and tumor progression." (PMID 23405127, 2013).
tumor (continued). "Sequencing revealed that AR F876L predominated in one tumor (∼71%), was present at low frequency in four other tumors (∼1 to 2%), and that a distinct amino acid substitution at this residue, F876I, was enriched in one enzalutamide-resistant tumor." (PMID 23580326, 2013). "A hormonal effect may also be involved in tumor formation, based on the deregulation of androgen receptor (AR)." (PMID 23354516, 2013). "Similarly, in the HPCa101 patient tumor (GS9), most tumor cells were positive for nuclear AR but moderately positive for CK8 and PSA, perhaps due to their overall poorly differentiated nature." (PMID 23451107, 2013). "A third molecule, 17-benzoimidazole TOK-001, has combined CYP17/AR inhibitor activity and has shown promising results in preclinical studies including a remarkable decrease in AR protein expression and regression of in vivo xenograft tumours." (PMID 23573093, 2013). "Collectively, these data highlight the possibility that sole expression of AR in tumor cells may not only be a prognostic indicator but also a therapeutic target." (PMID 24324894, 2013). "However, we did not detect significant association of double positive of P-STAT3 and ALDH1 with the clinical or pathological features such as tumor size, histological type, grade, lymph node or distant Metastasis, AR, ER, PR, and HER2." (PMID 24376586, 2013). "Furthermore, there is a strong potential for these other novel forms of AR inhibitors to be used synergistically with potent clinically used anti-androgens, such as enzalutamide, to achieve a more substantial anti-tumour response." (PMID 23771019, 2013). "Intra-tumoral synthesis of androsterone and androstanediol could stimulate tumor growth not only as intermediate steroids in DHT synthesis, but also as potent AR activators in cases with mutated ARs." (PMID 24244276, 2013). "Later a potential synergistic effect from the combination of phytochemicals in BCE was hypothesized because tumor cell proliferation and androgen receptor expression were more affected by BCE than by the pure isoflavone tectorigenin alone." (PMID 23969837, 2013). "Intra-tumor variability is most prominent with the AR copy number in primary tumors." (PMID 24098661, 2013). "The factors that modify the function of AR might influence the progression of tumor to a castration-resistant state during ADT." (PMID 23359804, 2013). "This new paradigm for targeting constitutively active AR and its tumor specific splicing isoforms using andro-miRs may pave the way for a novel adjunctive therapy and improved treatment of CRPC." (PMID 26877888, 2013). "By integrating sequence analysis, transcriptome profiling, cell viability assays and xenograft tumor growth inhibition studies, we explore the AR cistrome-activity relationship to render a global and dynamic view of its regulatory program upon small molecule antagonism." (PMID 22849360, 2012). "Besides tumor grade and Lauren type, the positivity of ERα and AR proteins also negatively correlates with advanced T and N classifications, and thereby correlates with an early TNM stage significantly." (PMID 23199240, 2012). "We describe a new somatic mutation in the AR 5'UTR which is found in two independent tumours and is not a normal polymorphism." (PMID 22471922, 2012). "Perhaps, one of the mechanism by which AR becomes oncogenic could be due to its inability to trans-activate tumor suppressors such as Id4 due to promoter hypermethylation." (PMID 23342267, 2012). "Taken together it appears that the androgen receptor in HCC may be more relevant for the biology of the tumor than the androgens or antiandrogen treatment." (PMID 22647077, 2012). "Interestingly, a positive AR expression was detected in 14 of 25 (56%) of the non-KCNMA1 amplified tumours but in only one of nine (11%) KCNMA1 amplified tumours (p<0.05)." (PMID 22899999, 2012).